SHBG (sex hormone binding globulin)
Diseases named in the same sentence as SHBG in open-access papers (continued):
Sharing a sentence is not in itself a finding about the gene and the disease.
prostate carcinoma (continued). "It has been suggested that dietary fiber may reduce prostate cancer risk possibly by increasing circulating levels of sex hormone-binding globulin and improving insulin sensitivity." (PMID 26315558, 2015). "The genetic variation in SHBG was implicated to influence prostate cancer susceptibility." (PMID 24386165, 2013). "Fiber has been implicated in prostate cancer etiology; fiber increases sex hormone-binding globulin and improves insulin sensitivity, both of which may decrease risk of aggressive prostate cancer." (PMID 23213538, 2012). "Therefore, IGF-1 increases prostate cancer risk by reducing SHBG levels." (PMID 39781351, 2025). "Furthermore, some research indicates that low levels of sex hormone-binding globulin (SHBG) may predispose individuals to prostate cancer, as reduced SHBG results in a greater availability of free testosterone in the body." (PMID 39682196, 2024). "Hormones’ involvement in prostate cancer pathogenesis makes it difficult to precisely determine the risk factors, due to the complex interactions among several hormones (testosterone, 5-alpha reductase, sex hormone binding globulin (SHBG), oestrogens), and environment factors (diet, smoking, etc.)." (PMID 28255369, 2017). "Plasma SHBG levels are not only associated with a variety of benign endocrine diseases but also affect the incidence of several sex hormone-dependent malignancies, such as low levels of circulating SHBG may increase the risk of breast, endometrial, and prostate cancer." (PMID 38465341, 2024). "Our work demonstrated this in two prostate cancer cell lines, in which SHBG-bound T was internalized, resulting in KLK3 induction." (PMID 36875158, 2023). "Import of SHBG-bound T by megalin occurs most notably in kidney cells, but import of SHBG has also been shown in LNCaP prostate cancer cells." (PMID 36875158, 2023). "We report that megalin imports SHBG-bound T into prostate cells, is regulated by vitamin D, and is dysregulated in prostate cancer." (PMID 36875158, 2023). "There were significant interactions in the associations of total testosterone with overall and aggressive prostate cancer by SHBG concentrations." (PMID 35579976, 2022). "We investigated the associations of calculated free and measured total testosterone and sex hormone‐binding globulin (SHBG) with aggressive, overall and early‐onset prostate cancer." (PMID 35579976, 2022). "There were also eight, four and eight SNPs identified in the main IVW analyses of total testosterone, bioavailable testosterone and SHBG on prostate cancer, respectively." (PMID 35061662, 2022). "Sex-hormone binding globulin has been shown to have a protective effect in prostate cancer, by potentially impacting the estrogen/testosterone balance by binding to and sequestering testosterone and estradiol." (PMID 32292572, 2020). "A recent study showed that there is a relation between SHBG level and prostate cancer especially in younger patients." (PMID 27532110, 2016). "Identifying genetic factors that influence SHBG may provide insights into the biology of sex steroid hormone regulation, metabolism and tissue effects that underlie their relationship with chronic diseases such as T2D as well as hormone-sensitive cancers such as breast and prostate cancer." (PMID 22829776, 2012). "For the exon 1B primer, the maximum levels were found in PZ-HPV7 cells, followed by PC3 cells, whereas with the exon 1C primer, similar levels of SHBG were found in the three prostate cancer cell lines." (PMID 19534810, 2009). "SHBG is a protein produced by the liver that binds to sex hormones, regulating their transport and availability in the bloodstream, SHBG levels can also influence the availability of sex hormones, with high SHBG levels related to decreased risks of breast and prostate cancers." (PMID 39839288, 2024).
prostate carcinoma (continued). "Given the lack of evidence for a causal effect on breast or prostate cancer risk, SHBG has been excluded from all further analyses, and total testosterone has been excluded from analyses of prostate cancer." (PMID 35061662, 2022). "Neither circulating total testosterone nor SHBG was associated with elevated risks for prostate cancer." (PMID 35579976, 2022). "Similarly, our findings that increasing SHBG reduces both breast and prostate cancer were consistent with previously reported MR results." (PMID 35061662, 2022). "Higher SHBG was associated with a lower risk (HR per 10 nmol/L increment = 0.95, 0.94‐0.97), neither was associated with prostate cancer mortality." (PMID 33252839, 2021). "Another opportunity that might merit further investigation would be to better define the role of SHBG in the efficiency and selectivity of imaging AR in prostate cancers, which proved to be a challenging problem to address in preclinical models." (PMID 32718075, 2020). "The comparison of prostatic volume, total testosterone, sex hormone binding globulin, free testosterone, bioavailable testosterone and albumin showed that patients with cancer of the prostate had significantly greater levels of free testosterone (p=0.043) and bioavailable T (p=0.049)." (PMID 27532110, 2016). "This study was to determine whether SHBG plays a role in testosterone uptake, metabolism, and action in the androgen sensitive LNCaP prostate cancer cell line." (PMID 27990161, 2016). "This study was designed to determine whether the androgen sensitive LNCaP prostate cancer cell line internalises SHBG; whether SHBG uptake affects Te uptake; the effects of SHBG on Te function and metabolism; and the effects of SHBG and Te on cell growth." (PMID 27990161, 2016). "As in the case of the prostate cancer cell lines, upper-than-expected RT-PCR bands were detected (β band) that, once sequenced, corresponded to specific SHBG transcripts whose exon 1A and 1B sequences were followed by the exon 1 sequence using the 3' splice sites a and b." (PMID 19534810, 2009). "Previous prospective studies have shown that higher SHBG and lower IGF-I concentrations are associated with lower risks of breast and prostate cancer, and thus the differences in these biomarker concentrations by diet group might suggest a lower risk of these cancers in vegetarians and vegans." (PMID 34132352, 2021). "To analyze the activity of the different SHBG transcription units in prostate tissues and prostate cancer cell lines, we performed RT-PCR using specific forward primers for each of the alternative first exons, as well as an exon 3 forward primer, to determine the global SHBG expression." (PMID 19534810, 2009). "In this randomized controlled dietary intervention study of patients with prostate cancer, an increased intake of phytoestrogens did not affect the serum of concentrations of testosterone, SHBG, and IGF-1." (PMID 37049632, 2023). "The definitive experiments to test the role of SHBG would involve comparing these two in nonhuman primates, as we had done earlier with rather different compounds, or better yet, in men with prostate cancers." (PMID 32718075, 2020). "Materials and methods: The concentrations of sex hormones, including testosterone (total, free, and bioavailable), sex hormone-binding globulin (SHBG), luteinizing hormone (LH), and follicle-stimulating hormone (FSH), were measured in 415 patients diagnosed with prostate cancer." (PMID 32365474, 2020). "However, another study reported that SHBG level was not predictive of the diagnosis or aggressiveness of prostate cancer." (PMID 32365474, 2020). "LNCaP prostate cancer cells transfected with several SHBG constructs containing exons 2 to 8 but lacking the 5′UTR sequence did show SHBG translation, whereas inclusion of the 5′UTR sequences of either exon 1A or 1B caused a dramatic decrease in SHBG protein levels." (PMID 21079794, 2010).
prostate carcinoma (continued). "In conclusion, our findings suggest that a high intake of phytoestrogens may lower the concentration of estradiol in patients with prostate cancer with a specific genetic upset of ERβ but does not affect serum concentrations of testosterone, IGF-1, and SHBG." (PMID 37049632, 2023).
Infertility (52 papers, 2005 to 2025). "Compared to a pro-inflammatory pro-oxidative diet, an anti-inflammatory anti-oxidative diet reduced the risk of infertility by 51% and increased levels of SHBG by 14.54 nmol/L." (PMID 40458178, 2025). "For DOBS, participants in T3 had significantly lower risk of infertility (OR: 0.62, 95% CI 0.39-1.01) and higher SHBG levels (OR: 1.62, 95% CI 1.20-2.19) compared to those in T1." (PMID 40458178, 2025). "In the model that adjusts for all confounding, the highest DII tertile was associated with increased risk of infertility and low-SHBG." (PMID 40458178, 2025). "Consuming foods with higher DII was significantly associated with higher risk of infertility (OR: 1.86; 95% CI: 1.20-2.89) and lower levels of SHBG (β: -9.98; 95% CI: -19.45–0.51)." (PMID 40458178, 2025). "We identified a significant positive correlation between elevated SUA levels and an increased risk of infertility in women, with SHBG partially mediating this association." (PMID 39006368, 2024). "The causal relationship between SHBG and infertility was examined using inverse variance weighted, weighted model, weighted median, and MR-Egger regression analyses." (PMID 38848344, 2024). "The OR was 0.854 (95% CI: 0.793–0.919; P=2.853e-05), suggesting a 14.60% increased risk of infertility per standard deviation increase in SHBG levels." (PMID 39006368, 2024). "Establishing a causal relationship between SHBG levels and infertility holds significant implications for those affected by infertility." (PMID 38848344, 2024). "JMJD1C, a member of the Jumonji-domain containing histone demethylases protein family, has been associated with levels of sex-hormone binding globulin (SHBG) and testosterone in men, and knock-out rodent models show age-dependent infertility." (PMID 29222425, 2017). "Secondly, due to the small number of women in the control group with infertility, we were unable to conduct a representative comparative analysis of the genetic characteristics of patients and controls with infertility according to the considered SHBG-significant polymorphisms." (PMID 41373783, 2025). "However, anti-inflammatory and anti-oxidative diets reduced the risk of infertility by 51% and increased SHBG levels by 14.54 nmol/L." (PMID 40458178, 2025). "This study demonstrates that the dietary potential for inflammation and oxidative stress, as indicated by scores derived from pro-inflammatory and anti-oxidative dietary components in an individual’s diet, are linked to an increased risk of infertility and lower levels of SHBG." (PMID 40458178, 2025). "Additionally, women who consumed anti-inflammatory and anti-oxidative diets had lower risk of infertility (OR: 0.49, 95% CI 0.28-0.82) and higher SHBG levels (OR: 1.67, 95% CI 1.19-2.33)." (PMID 40458178, 2025). "Therefore, we investigated the causal relationship between SHBG levels and infertility using a Mendelian randomization (MR) study." (PMID 38848344, 2024). "Additionally, the significant mediating effect of BMI and WC suggests that anti-inflammatory and/or anti-oxidant diets for weight loss may be an effective way to prevent infertility and low SHBG levels." (PMID 40458178, 2025). "Thus, we used an MR analysis as a hypothesis-generating method to determine if there is a causal relationship between SHBG and infertility." (PMID 38848344, 2024). "Some authors report azoospermia and infertility in males, while others describe alterations in sex hormone-binding globulin (SHBG) and LH in patients with chronic kidney disease." (PMID 41480351, 2025). "Given the significant impact of age and BMI on SHBG levels and the subsequent availability of testosterone, it is crucial to consider these factors when formulating a management strategy for infertile men with hypogonadal conditions." (PMID 40747475, 2025). "A considerable number of growing infertile couples around the globe encourages the research, thus the link between infertility and SHBG concentration is being widely discussed." (PMID 40427034, 2025).
Infertility (continued). "There were significant linear relationships between the DII and DOBS, and infertility and serum SHBG (p for overall < 0.05)." (PMID 40458178, 2025). "The causal relationship between sex hormone-binding globulin (SHBG) and infertility has remained unclear." (PMID 38848344, 2024). "The relationship between SUA and infertility is further complicated by the involvement of factors like Sex Hormone-Binding Globulin (SHBG) and reproductive hormones, especially in conditions like PCOS, where evidence remains conflicting." (PMID 39006368, 2024). "SHBG expression offers protection against the development of certain types of female infertility, suggesting it is a potential therapeutic target for infertility." (PMID 38848344, 2024). "The effects of SHBG on infertility were also assessed using the IVW method, and consistent estimates were obtained using the Weighted median method (OR = 0.764, 95% CI = 0.6–0.974, P = 0.03)." (PMID 38848344, 2024). "Among the different types of infertility tested, SHBG was negatively correlated with specific categories, such as infertility associated with anovulation." (PMID 38848344, 2024). "Elevated SUA levels significantly decrease SHBG levels (β=-0.261; P=2.177e-04), with SHBG mediating 27.93% of the effect of SUA on infertility (OR=0.854; 95%CI, 0.793–0.920; P=2.853e-05)." (PMID 39006368, 2024). "The study further confirmed that SHBG serves as a protective factor in anovulatory infertility in women." (PMID 38848344, 2024). "The continuous increase in insulin levels stimulates the ovaries to secrete excessive androgens and decrease hepatic SHBG, ultimately aggravating abnormalities in the hypothalamus-pituitary-ovarian axis, ovulation disorders and infertility." (PMID 37974132, 2023). "OCs alleviate the clinical symptoms by inducing a combination of anovulatory infertility, regular pseudo-menses and pharmacological elevations of sex hormone-binding globulin (SHBG)." (PMID 37715279, 2023). "In a study of 24 men recruited through a US infertility clinic, concentrations of BDE-47, BDE-99, and BDE-100 in house dust were positively associated with inhibin B and SHBG." (PMID 36430706, 2022). "Age, BMI, CCI, tT and SHBG were similar among infertile men as segregated according to semen parameter’s alterations." (PMID 34097690, 2021). "On the contrary, the median GPX and SHBG were significantly lower among infertile smokers as compared to fertile smokers." (PMID 31736779, 2019). "The importance of SHBG in PCOS lies in the fact that measurements of serum SHBG concentrations can act as an appropriate predictor of response to pharmacological treatment in infertile women with PCOS." (PMID 40871560, 2025). "In RCS regression, after adjusting for different covariates, we detected significant linear relationships between continuous DII/DOBS and infertility risk and dichotomous SHBG (p for overall <0.05, p for nonlinear >0.05)." (PMID 40458178, 2025). "The determination of SHBG level in women with PCOS and infertility seems to be justified as this parameter directly affects the level of androgenization in PCOS, and normal SHBG levels are a protective factor in the case of infertility caused by anovulation." (PMID 40427034, 2025). "Additionally, women with PCOS and infertility due to anovulation should have their SHBG levels tested." (PMID 40427034, 2025). "However, some study reported that thiazolidinediones (i.e., PPAR-γ agonists) led to an increase in plasma SHBG levels and improved anovulation and ovulatory dysfunction and infertility in patients with PCOS." (PMID 38848344, 2024). "MR results on sex hormone binding globulin (SHBG) and infertility." (PMID 38848344, 2024). "Our findings revealed a significant negative association between sex hormone-binding globulin (SHBG) levels and infertility, particularly with anovulation, a specific form of female infertility." (PMID 38848344, 2024).
Infertility (continued). "The results of the two-sample MR analysis showed that SHBG is a protective factor against the development of infertility and could be used as a potential biomarker and therapeutic target for infertility." (PMID 38848344, 2024). "Cochran’s Q test results on sex hormone binding globulin (SHBG) and infertility." (PMID 38848344, 2024). "Furthermore, in women with PCOS, the level of homocysteine is inversely correlated with the level of transporting protein (SHBG), with circulatory system diseases and infertility." (PMID 33652684, 2021). "After weight loss surgery, a steep increase of SHBG and decline of testosterone, androstenedione, and DHEA-S levels were observed in obese women, which might help to overcome menstrual anomalies and infertility." (PMID 29973985, 2018). "Therefore, serum SHBG levels could serve as useful biomarker for the diagnosis and potential therapeutic target infertility." (PMID 38848344, 2024). "Therefore, SHBG could prevent the occurrence and development of infertility by jointly acting through these two mechanisms." (PMID 38848344, 2024). "The improved biochemical measures of PCOS included androgen levels, lipids, HOMA-IR, blood glucose, insulin, LH/FSH ratio, DHEAS, SHBG, AFC, and AMH, while the improved symptoms of PCOS were irregular menstruation, infertility, OHSS, and weight gain." (PMID 40944281, 2025). "The reproductive subtype was identified by comparatively low body mass index (BMI) and insulin levels, as well as greater levels of LH and sex hormone-binding globulin (SHBG) and more severe infertility and irregular menstruation." (PMID 38389707, 2024). "SHBG provides protective effects against anovulation-type infertility in women and manifests a negative correlation with BMI in men." (PMID 40427034, 2025). "Infertility (yes or no, self-reported in questionnaire) and serum gonadal hormones including total testosterone (TT), estradiol (E2), and sex hormone-binding globulin (SHBG) were considered as main outcome variables." (PMID 40458178, 2025). "Egger intercept analysis of sex hormone binding globulin (SHBG) and infertility." (PMID 38848344, 2024). "Previous research has predominantly focused on the relationship between SHBG and ovarian dysfunction or metabolic disorders in patients with PCOS without further analyzing SHBG as a protective factor in female patients with infertility." (PMID 38848344, 2024). "Fifth, serum concentrations of free T, androstenedione, and sex hormone-binding globulin (SHBG) were not measured in our routine infertility evaluation." (PMID 33737663, 2021). "Fifth, serum free T and sex hormone-binding globulin (SHBG) levels were not measured in our routine infertility survey." (PMID 33803980, 2021). "In this population of infertile patients, hormonal values were reported as follows (mean ± SD): LH 4.2 ± 3.6 mUI/mL; FSH 7.9 ± 3.2 mUI/mL; T 4.6 ± 1.5 ng/mL; E2 27.2 ± 5.4 pg/mL; DHT 0.21 ± 0.2 ng/mL; SHBG 35.7 ± 5.8 nmol/L, PRL 11.5 ± 3.4 ng/ml." (PMID 29410650, 2017). "However, we did another analysis via collecting serum estradiol, total testosterone, and sex hormone binding globulin levels available in 2013–2016 NHANES datasets as parts of covariates and found the association between inflammatory markers and infertility remained consistent (results not shown)." (PMID 38238731, 2024). "However, age, BMI, duration of infertility, estradiol levels, total testosterone, prolactin, TSH, and SHBG concentrations were not significantly different between normo-androgenic PCOS and NOR patients." (PMID 33992122, 2021).